CHFR (checkpoint with forkhead and ring finger domains)
Diseases named in the same sentence as CHFR in open-access papers (continued):
Sharing a sentence is not in itself a finding about the gene and the disease.
breast cancer (8 papers, 2008 to 2024). A primary or metastatic malignant neoplasm involving the breast. "High levels of Aurora A in mammary cancers cannot therefore be explained by a loss of function of CHFR." (PMID 18335050, 2008). "To determine the correlation of CHFR expression with clinical outcome, we analyzed a cohort of human breast cancer patients in which transcriptomic profiling was obtained from 84 mesenchymal/basal subtype tumor samples." (PMID 34462429, 2021). "It is established that CHFR is silenced in many primary cancers including breast cancers due to CpG methylation and histone deacetylation." (PMID 34462429, 2021). "In a breast cancer cell line model, decreased CHFR expression resulted in an accelerated growth rate, enhanced invasiveness and amplified colony formation." (PMID 24375389, 2014). "Whereas ZEB1 has been shown to confer different types of cancer drug resistance including in breast cancer, the function of CHFR in chemoresistance of TNBC cells remains unclear." (PMID 34462429, 2021). "Moreover, we analyzed 177 mesenchymal subtype breast cancer patients with systematic treatment including conventional chemotherapy and found that low expression of CHFR confers mesenchymal breast cancers resistant to chemotherapy (P = 0.029)." (PMID 34462429, 2021). "In patients with basal-like breast cancers, CHFR levels significantly correlates with survival." (PMID 34462429, 2021). "Collectively, these data suggest that downregulation of CHFR may contribute to overexpression of ZEB1 in human malignant breast tumors, which may lead to chemoresistance and eventually metastatic relapse." (PMID 34462429, 2021). "We need to pay attention to the tissue specificity of CHFR to induce the degradation of Aurora A. Elevated protein levels of Aurora A are frequently observed in both human colon and mammary cancers, but the inactivation of CHFR is limited to cases of colon cancer." (PMID 18335050, 2008). "BPA induced hypermethylation of TIMP3, CHFR, ESR1, and IGSF4 while HBCD induced TIMP3 tumor suppressor gene hypermethylation in MCF7 breast cancer cell line." (PMID 32466334, 2020). "We observed that BPA induced hypermethylation of TIMP3, CHFR, ESR1, and IGSF4 while HBCD induced TIMP3 tumor suppressor gene hypermethylation in MCF7 breast cancer cell line." (PMID 32466334, 2020). "However, it is not clear whether CHFR expression will benefit the treatment for resistant breast cancers." (PMID 34462429, 2021). "In male breast cancer, methylation was very rare in BRCA1, CDKN2A, VHL, ATM and CHFR (< 2%) - indicating that methylation of these genes does not seem to play a prominent role in male breast carcinogenesis." (PMID 22765268, 2012). "Interestingly, a significant negative correlation between CHFR and ZEB1 was observed in these breast cancer cells, in which most of the tumors with high ZEB1 expression exhibited low CHFR expression." (PMID 34462429, 2021).
cervical carcinoma (7 papers, 2007 to 2023). A carcinoma arising from either the exocervical squamous epithelium or the endocervical glandular epithelium. "We previously showed a relationship between aberrant methylation of CHFR and sensitivity to taxanes, and suggested that aberrant methylation of CHFR could serve as a molecular marker for the sensitivity of cervical cancer to anticancer drugs." (PMID 22797812, 2012). "These researches demonstrated us that FHIT and PTEN in Hela cells and FHIT and CHFR in Siha cells might have the other regulation pathways for carcinogenesis or transcription control, and which needs more tests of cervical cancer cells and clinical specimens." (PMID 21999220, 2011). "Currently, the known repressor genes are related to cervical cancer including CCNA1, CHFR, FHIT, PAX1, PTEN, SFRP4, TSLC1 and etc." (PMID 21999220, 2011). "Methylation of CHFR, CDH13 and CADM1 was only observed in cervical carcinomas and cervical carcinoma cell lines and can as such be designated as relative late events." (PMID 17971771, 2007). "Cervical carcinoma cell lines, showed next to markers present in FK cell lines, also revealed frequent methylation of CADM1 and CHFR." (PMID 17971771, 2007). "Notably, all eight genes that were frequently methylated in the HPV-transfected cell lines and cervical cancer cell lines (i.e. TP73, ESR1, RARβ, DAPK1, MGMT, CADM1, CDH13 and CHFR) overlapped with those found to be methylated in the cervical carcinoma specimens." (PMID 17971771, 2007).
colon cancer (6 papers, 2008 to 2020). "In our current study, we have investigated the molecular pathways underlying the growth suppressive functions of CHFR by utilizing genetic rescue experiments with colon cancer cell lines in which endogenous CHFR is epigenetically inactivated." (PMID 18335050, 2008). "The inactivation of CHFR may thus cause the up-regulation of these proteins, which are known mitotic kinases and are frequently observed to be overexpressed in various types of human malignant tumors, such as bladder and colon cancers." (PMID 18335050, 2008). "The endogenous levels of CHFR mRNA were measured by real-time RT-PCR in five pancreatic cancer cell lines and six colon cancer cell lines." (PMID 18335050, 2008). "Colon cancer cells have lost the endogenous expression of CHFR, and we thus anticipated that this would be an appropriate cell system to elucidate the functional domain responsible for the anti-proliferative effects of CHFR protein by genetic rescue." (PMID 18335050, 2008). "The protein levels of Aurora A did not change after the expression of any form of CHFR in HCT116 colon cancer cells in our current experiments (data not shown)." (PMID 18335050, 2008). "CHFR transcripts were detectable in each of the pancreas cell lines tested but three colon cancer derived cell lines, HCT116, RKO and DLD1, showed no expression of CHFR mRNA." (PMID 18335050, 2008).
esophageal squamous cell carcinoma (6 papers, 2014 to 2024). Esophageal squamous cell carcinoma (ESCC) is a type of esophageal carcinoma (EC) that can affect any part of the esophagus, but is usually located in the upper or middle third. "CHFR methylation can be used to determine the extent of esophageal squamous-cell carcinoma and the efficacy of chemotherapy with docetaxel and paclitaxel." (PMID 39766341, 2024). "For example, Hypermethylated CDKN2A and CHFR were assessed as biomarkers for predicting radio resistance in esophageal squamous cell carcinoma." (PMID 37626750, 2023). "In conclusion, CHFR is frequently methylated in human esophageal squamous cell carcinoma and the expression of CHFR is regulated by promoter region methylation." (PMID 25821560, 2015). "Using RT-PCR, CHFR gene expression in 40 primary esophageal squamous cell carcinomas was quantified." (PMID 24348823, 2014). "Studies have shown that the degree of CHFR methylation may be treated as a biomarker in the early stages of esophageal squamous-cell carcinoma." (PMID 39766341, 2024). "The methylation changes of CHFR during carcinogenesis and the sensitivity of esophageal squamous cell carcinoma to taxanes remain unclear." (PMID 25821560, 2015). "It suggests that CHFR methylation is a late stage marker of esophageal squamous cell carcinoma." (PMID 25821560, 2015).
esophageal adenocarcinoma (4 papers, 2014 to 2021). A malignant tumor with glandular differentiation arising predominantly from Barrett mucosa in the lower third of the esophagus. "Other data have shown that the interplay between epigenetic and genetic mechanisms underlies the loss of CHFR function in esophageal adenocarcinoma, indicating that there are various steps involved in suppressing mRNA expression of the CHFR gene." (PMID 24348823, 2014).
bladder cancer (3 papers, 2023 to 2025). "Another previous study reported elevated expression of the cis-SAGes BCL2L2-PABPN1 and CHFR-GOLGA3, predominantly localized in the nucleus, in bladder cancer." (PMID 41155268, 2025).
lymph node metastasis (3 papers, 2017 to 2020). "CHFR methylation was significantly associated with the positive lymph node metastasis, OR was 1.56 with 95% CI 1.05–2.32, p = 0.03." (PMID 29515792, 2018). "Our pooled data showed CHFR promoter hypermethylation significantly increased the risk of lymph node metastasis in CRC patients." (PMID 29179506, 2017). "Additionally, our finding indicated that CHFR promoter methylation was strongly associated with lymph node metastasis." (PMID 29515792, 2018). "CHFR promoter methylation is associated with tumor poor differentiation and lymph node metastasis." (PMID 29515792, 2018). "Noteworthy, Henriksen and colleagues disclosed that CHFR gene methylation was involved in lymph node metastasis in patients with PC." (PMID 32943033, 2020). "The frequency of CHFR methylation in different status of lymph node metastasis was evaluated, our findings demonstrated that the CHFR methylation occurred more frequently in GC patients with lymph node metastasis in contrast to the patient without lymph node metastasis." (PMID 29515792, 2018).
non-small cell lung carcinoma (3 papers, 2014 to 2023). A group of at least three distinct histological types of lung cancer, including non-small cell squamous cell carcinoma, adenocarcinoma, and large cell carcinoma. "Additional studies to identify structural variations in the CHFR coding sequence led to the identification of three missense mutations in non-small cell lung cancer (NSCLC); all three were associated with a defective mitotic checkpoint." (PMID 24375389, 2014).
ovarian carcinoma (3 papers, 2012 to 2018). A malignant neoplasm originating from the surface ovarian epithelium. "Yet in our study, we found that DNMT1 knockdown alone induced CHFR promoter hypomethylation significantly in A2780 and 3AO cells, which, in turn, led to increased expression of CHFR mRNA and protein in ovarian cancer cell lines." (PMID 29367628, 2018). "Our findings suggest that CHFR via Aurora A participates in UBC13 regulation of paclitaxel sensitivity in ovarian cancer cells." (PMID 29367628, 2018). "Moreover, CHFR promoter methylation status was higher and the CHFR mRNA level was lower in paclitaxel-resistant ovarian cancer cells." (PMID 29367628, 2018). "Moreover, CHFR decrease was consistent with UBC13 decline when ovarian cancer cells were exposed to paclitaxel." (PMID 29367628, 2018). "Thus, our findings suggest that CHFR acts as a positive modulator in the process of UBC13 regulating paclitaxel sensitivity in ovarian cancer cells." (PMID 29367628, 2018). "Then, we examined CHFR influence on the paclitaxel sensitivity of ovarian cancer cells." (PMID 29367628, 2018). "Our results suggest that DNMT1 regulates CHFR expression by altering its promoter DNA methylation in ovarian cancer cells, but such a regulating effect may be variable among different cancers." (PMID 29367628, 2018). "Since DNMT1 is one of the DNA methyltransferases, we knocked down DNMT1 by specific siRNAs and observed whether genetic reduction of DNMT1 altered the methylation of the CHFR promoter and the expression of CHFR in ovarian cancer cells." (PMID 29367628, 2018). "Moreover, a reverse regulation of CHFR partally eliminated the resistance to paclitaxel induced by UBC13 regulation in ovarian cancer cells." (PMID 29367628, 2018). "In the present study, we found that CHFR overexpression decreased the level of Aurora A, and elevated the sensitivity to paclitaxel; and conversely, CHFR reduction increased the level of Aurora A and reduced the sensitivity to paclitaxel in ovarian cancer cells." (PMID 29367628, 2018). "Our findings together suggest that UBC13 controls DNMT1 stability via ubiquitination and DNMT1, probably through CHFR and Aurora A, participates in UBC13 regulation of the sensitivity of ovarian cancer cells to paclitaxel." (PMID 29367628, 2018). "Moreover, the paclitaxel resistant ovarian cancer cells (A2780-TR and SKOV3-TR30) presented higher CHFR promoter methylation status and lower CHFR mRNA levels than sensitive parental cells." (PMID 29367628, 2018). "Thus, our findings suggest that paclitaxel induces UBC13 down-regulation, which facilitates cell resistance to paclitaxel, and a pathway consisting of DNMT1, CHFR, and Aurora A probably participates in UBC13 regulation of the sensitivity to paclitaxel in ovarian cancer cells." (PMID 29367628, 2018). "Furthermore, down-regulated CHFR inhibited paclitaxel sensitivity, elevated Aurora A expression, but did not affect DNMT1 and UBC13 in ovarian cancer cells, and vice versa." (PMID 29367628, 2018).
adenoma (2 papers, 2008 to 2014). A neoplasm arising from the epithelium. "Since the promoter methylation of the CHFR gene was detected in non-invasive adenoma lesions of colon epithelia, the associated loss of the checkpoint function of CHFR in these cells may have a significant impact upon the early stages of colon carcinogenesis." (PMID 18335050, 2008). "In particular, higher methylation levels of CDKN2B, RASSF1, CHFR, BRCA2 and IGSF4 were observed in adenomas that recurred." (PMID 25091577, 2014).
oral cancer (2 papers, 2020 to 2022). "We found that a combination of six genes (TP73, CASP8, RARB, KLLN, GSTP1, and CHFR) could distinguish oral cancer from clinically diagnosed OPMDs with high diagnostic performance (area under the curve [AUC], 0.885; sensitivity, 77.8%; and specificity, 87.1%)." (PMID 35681626, 2022). "Evaluation of the combination of six genes with aberrant methylation (RARB, KLLN, CHFR, TP73, GSTP1, and CASP8) was particularly useful for identifying early-stage oral cancer in clinically diagnosed patients with OPMDs with high diagnostic performance." (PMID 35681626, 2022). "IL-6 also induced promoter hypermethylation of several important TSGs, namely CHFR, GATA5, and PAX6, in oral cancer cells." (PMID 32678024, 2020).
squamous cell carcinoma (2 papers, 2017 to 2018). A carcinoma arising from squamous epithelial cells. "Further subgroup analysis revealed that CHFR promoter was more frequently methylated in squamous cell carcinoma (SCC) than in adenocarcinoma (ADC), OR was 4.46 with 95% CI 1.65–12.05, p = 0.003, suggesting the mechanism of SCC pathogenesis is different from ADC." (PMID 29312643, 2017).
atherosclerosis (1 paper, 2024). A disease characterized by the build-up of fatty material and calcium deposition in the arterial wall resulting in partial or complete occlusion of the arterial lumen. "Moreover, five notable crosstalk pathways, circ-UBR4/miR-637/FOXO4, circ-UBR4/miR-107/ROCK1, circ-UBR4/miR-491-5p/NRP2, circ-UBR4/miR-185-5p/FRS2 and circ-CHFR/miR-214-3p/PAPPA axis, regulate VSMC migration and growth to improve atherosclerosis." (PMID 38515760, 2024). "Moreover, circ-CHFR could contribute to human VSMC growth and migration as well as atherosclerosis deterioration via the circ-CHFR/miR-214-3p/PAPPA axis." (PMID 38515760, 2024).
colorectal adenocarcinoma (1 paper, 2021). The most common type of colorectal carcinoma. "The promoter methylation of CHFR has been described in several tumor types, such as gastric and colorectal adenocarcinoma, and has been also described as a potential biomarker for taxanes, irinotecan, or poly (ADP-ribose) polymerase (PARP) inhibitors sensitivity." (PMID 34869418, 2021).
endometrial cancer (1 paper, 2012). Primary or metastatic malignant neoplasm involving the endometrium (mucous membrane that lines the endometrial cavity). "Reduced expression of genes such as APC, CHFR, Sprouty 2, RASSF1A, GPR54, CDH1, and RSK4 through a similar mechanism of hypermethylation has also been found in endometrial cancer." (PMID 22548175, 2012).
epithelial dysplasia (1 paper, 2022). "In addition, methylation of KLLN, CHFR, TP73, GSTP1, and CASP8 may be related to precancerous processes, such as epithelial hyperplasia and epithelial dysplasia." (PMID 35681626, 2022).
gastric adenocarcinoma (1 paper, 2021). "In line with what has been recently described in gastric adenocarcinoma, linking the lack of CHFR expression and a higher sensitivity to PARP, it could be worthwhile to test the CHFR status in patients treated with this kind of drug family." (PMID 34869418, 2021).
head and neck cancer (1 paper, 2013). A primary or metastatic malignant neoplasm affecting the head and neck. "This hypomethylated set of genes included many genes that have previously been shown to be methylated in head and neck cancer, including RASSF1, CHFR, RUNX3, APC, and CDKN2A (p16)." (PMID 23358896, 2013).
hepatocellular carcinoma (1 paper, 2024). A malignant tumor that arises from hepatocytes. "The methylation of specific genes, including VASH2, CHFR, GRID2IP, CCNJ, SEPT9, and F12, is considered a biomarker for the onset of hepatocellular carcinoma (HCC)." (PMID 38473997, 2024).
nasopharyngitis (1 paper, 2018). An inflammatory process that affects the nasopharynx. "Among the six TSGs examined, the relative expression levels of CHFR, RIZ1, and CACNA2D3 in tissue samples were significantly decreased in NPC patients compared with those in nasopharyngitis patients (all P < 0.05)." (PMID 29764493, 2018).
Oral squamous cell carcinoma (1 paper, 2020). "For instance, the downregulation of CHFR in Oral squamous cell carcinoma cells was found to be effective in increasing the response to docetaxel." (PMID 32943033, 2020).
pancreatic ductal adenocarcinoma (1 paper, 2021). An infiltrating adenocarcinoma that arises from the epithelial cells of the pancreas. "Checkpoint with forkhead-associated and ring finger domains (CHFR) has been proposed as a predictive and prognosis biomarker for different tumor types, but its role in pancreatic ductal adenocarcinoma (PDAC) remains unknown." (PMID 34869418, 2021).
periodontitis (1 paper, 2024). An acute or chronic inflammatory process that affects the tissues that surround and support the teeth. "Beyond its role in periodontitis, IL-6 induces oral carcinogenesis by promoting the hypermethylation of tumor suppressor genes, such as CHFR, GATA5, and PAX6." (PMID 38612423, 2024).
serous ovarian cancer (1 paper, 2021). "Accordingly, differences in CHFR expression are unlikely to play a major role in paclitaxel sensitivity of high grade serous ovarian cancer." (PMID 34885153, 2021).